CCR7 (C-C motif chemokine receptor 7)
Diseases named in the same sentence as CCR7 in open-access papers (continued):
Sharing a sentence is not in itself a finding about the gene and the disease.
breast cancer (continued). "Overall, the cells that express CCR7 within breast cancer tissue are often not clearly defined; however, immunohistochemistry of paraffin-embedded tissue sections suggested that CCR7 can be expressed by spindle-shaped stromal cells in different types of breast cancer." (PMID 35203305, 2022). "Given the role that CCR7 has in other tumors, such as breast cancer, in promoting proliferation, it could be useful to examine the effect of knocking down CCR7 on the survival of bone tumors, although CCR7 does not appear to have a significant role in bone cancers." (PMID 35203305, 2022). "Herein our study provides evidence that the expressions of both CCR7 and VEGF-C were significantly upregulated in the analyzed breast carcinoma samples when compared with control non-tumor tissues." (PMID 25744065, 2015). "Melanoma shares a similar metastatic phenotype to breast cancer, which also expresses high levels of CXCR4 and CCR7, but unlike breast cancer, experiences frequent metastasis to the skin." (PMID 24259307, 2013). "Furthermore, the depletion of CCR7 in BALB/c mice inhibited orthotopically injected 4T1 cells metastasis, while tail veins’ injection had no impact on breast cancer metastasis." (PMID 32340161, 2020). "The interaction between CCR7 and AP1 complex in breast cancer is not clear." (PMID 30781353, 2019). "Knockdown of CCR7 expression by siRNA had no impact on the migratory activity of parental M13SV1-EGFP-Neo breast epithelial cells exhibiting stem cell properties and HS578T-Hyg breast cancer cells as compared to naïve and scRNA transfected cells." (PMID 23667660, 2013).
melanoma (97 papers, 2006 to 2026). A malignant, usually aggressive tumor composed of atypical, neoplastic melanocytes. "Expression of CCR7 in DCs was also demonstrated in live images in melanoma and associated with a better prognosis." (PMID 38780041, 2024). "The overexpression of CCR7 on melanoma cells caused a greater migration of these cells towards LECs, and the use of a CCL21-neutralising antibody stopped their migration in vitro." (PMID 34830780, 2021). "More importantly, high expression of CCR7 by melanoma cells is associated with a worse patient outcome." (PMID 30420855, 2018). "High CCR7 expression has been associated with lymph node metastases and poor prognosis in oral squamous cell carcinoma and melanoma." (PMID 21548969, 2011). "However, CCR7 is upregulated in cancer, such as melanoma, and its expression seems to be linked to cancer aggressiveness, as CCR7 expression is higher in metastatic melanoma cells than in melanoma cells at the primary tumour site." (PMID 37170733, 2023). "Gene expression studies at the mRNA level have shown that human melanoma cell lines express CXCR4 and also receptors CCR10 and CCR7 which could be implicated in the frequent metastasis of melanoma to skin and lymph nodes, respectively." (PMID 24559071, 2014). "Similarly, CCL21/CCR7 pair seems to play an important role in the lymphangiogenesis associated with pancreatic cancer and – due to its chemotactic properties – this chemokine axis is involved in the lymphatic spread of melanoma cells." (PMID 25744065, 2015). "Exposure of mature cDC2s to melanoma-derived CM led to the downregulation of surface galectin-9 and CCR7 expression levels." (PMID 40986321, 2025). "Extensive work in cancer immunotherapy has shown that the CCL21/CCR7 expression axis promotes growth and metastasis in a variety of tumor types, including melanoma, breast, thyroid, colon, head, and neck cancers." (PMID 37426658, 2023). "In vitro experiments showed that A375 cells derived from a malignant melanoma expressed CCR7, producing chemotaxis towards CCL21, which was prevented by CCL21 neutralizing antibodies, such as B16 melanoma cells." (PMID 35203305, 2022). "For instance, sterol metabolism factors derived from human melanoma cell lines as well as colon, lung, and kidney carcinomas can inhibit CCR7 expression by triggering LXR-α activation." (PMID 35281921, 2022). "Between 1 and 5% of melanoma cells per cell line was identified as highly CCR7 positive co-expressed with two immune checkpoint ligands, PD-L1 and galectin-9, and had cancer stem cell characteristics." (PMID 35203305, 2022). "Expression of CXCR4, CCR7 and CCR10 on the surface of melanoma cells is associated with a poor prognosis." (PMID 35158973, 2022). "Analysis of several melanoma cell lines and tumor samples showed heterogeneous CCR7 expression as measured by quantitative real-time reverse transcriptase PCR, with CCR7 levels corresponding to CCL21 migration." (PMID 35203305, 2022). "A more recent study looked at CCR7 expression in 10 human melanoma cell lines derived from different anatomical locations." (PMID 35203305, 2022). "Loss of CCR7 or blockade of C-C motif chemokine ligand 21 (CCL21)/CCR7 axis abolished the pro-migration effect of PTX on B16F10 melanoma cells." (PMID 35280672, 2022). "Although non-melanoma skin cancer occurs far more frequently than melanoma, most studies on the role of CCR7 in skin cancer have focused on melanoma." (PMID 35203305, 2022). "By three weeks post injection, melanoma metastasis was evident in >50% of mice expressing CCR7 relative to 5% in controls." (PMID 35203305, 2022). "In melanoma cells, inhibitors of the epigenetic modifiers histone deacetylation or demethylation led to increased CCR7 expression and to increased cell migration." (PMID 35203305, 2022).
melanoma (continued). "In mice, the overexpression of CCR7 or CCR10 in B16 melanoma cells was shown to increase regional lymph node metastases, which was blocked by neutralizing its ligand, CCL21, using a specific antibody." (PMID 35158973, 2022). "It has previously been demonstrated that a population of CD56dimCD57+CD69+CCR7+KIR+ NK cells are expanded in tumour infiltrated lymph nodes of patients with melanoma, and that these NK cells are key effectors of anti-tumoral cytotoxicity." (PMID 35835762, 2022). "In this case, CCR7-expressing malignant melanoma cells were undergoing chemotaxis to CCL21 produced by lymphatic endothelial cells." (PMID 35203305, 2022). "A number of identified molecules, including TNFRSF13B, LAG3, NRP1, ENTPD1, NT5E, CCL21, and CCR7, can serve as future therapeutic targets in the treatment of melanoma." (PMID 34159752, 2021). "Melanoma cells exploit this same chemokine axis by upregulating CCR7 expression, enabling migration towards CCL21-producing LECs." (PMID 34830780, 2021). "The CCR7/CCL21 pathway coordinates the migration of melanoma cells towards and into lymphatic vessels." (PMID 34830780, 2021). "All such effects require CCR7 and high CCR7 expression levels in melanoma were found to be significantly related to T-cell infiltration and better clinical outcomes in patients." (PMID 33608497, 2021). "We have already discussed how melanoma is able to exploit the CCR7/CCL21 axis, but efforts have also been made to use this axis for therapeutic benefit." (PMID 34830780, 2021). "In vivo models have replicated these findings with CCR7-transduced B16 melanoma cells demonstrating greater metastasis to lymph nodes." (PMID 34830780, 2021). "Human lymph nodes express CCL21, while melanoma cells produce its receptor, CCR7, which is a key molecule mediating metastasis of many cancers." (PMID 33430277, 2021). "A number of identified molecules including TNFRSF13B, LAG3, NRP1, ENTPD1, NT5E, CCL21, and CCR7 can serve as future therapeutic targets in melanoma treatment." (PMID 34159752, 2021). "Specifically, studies have shown that the ectopic expression of the chemokine receptor CCR7 in murine melanoma cells increases tumor-lymph node and -brain tissue homing in vivo, whilst CXCR4 promotes melanoma-lung tropism." (PMID 30460237, 2018). "Spermine-dextran, a kind of cationic polymer-mediated gp100-melanoma antigen delivery showed anti-melanoma effect and CCR7 co-expression improved lymph node migration of transfected dendritic cells in vivo." (PMID 30680249, 2018). "In this sense, CCR7 bearing CD103+/CD141+ DCs are crucial for activating T cells inside tumor to increase melanoma rejection." (PMID 30425987, 2018). "The mature adipocyte-stimulated expression of CCL19 and CCL21 in lymphatic endothelial cell, and expression of their receptor CCR7 in melanoma cells, which contributes to increased lymph node metastasis of melanoma in high-fat diet-fed mice." (PMID 29137230, 2017). "Overexpression of CCR7 in melanoma has been shown to promote LN metastasis in mice, and CCR7 expression in human cancer samples correlates positively with LN metastasis." (PMID 28220121, 2017). "For instance, constitutive CCL21 expression by LEC can serve as a guide for CCR7-expressing breast cancer and melanoma cells invading the LNs." (PMID 28220121, 2017). "Enhanced CCR7 mRNA expression in human melanoma samples was also correlated to increased T cell infiltrates and improved patient outcomes." (PMID 29276510, 2017). "Upon incubation of CCR7 sorted, gene modified T cells with target melanoma cells, multifunctionality was largely unchanged compared to non-sorted T cells." (PMID 28239467, 2017). "The receptor CCR7 and its ligand CCL21 have been implicated in the lymphatic spread of tumor when CCR7 is expressed by melanoma cells and when CCL21 is expressed by lymphatic endothelial cells." (PMID 28952543, 2017).
melanoma (continued). "The C-C chemokine receptor type 7 (CCR7) promotes melanoma cell metastasis to the C-C motif ligand 21 (CCL21)-rich lymph nodes while the C-X-C chemokine receptor type 4 (CXCR4)/C-X-C motif chemokine ligand 12 (CXCL12) axis facilitates pulmonary metastasis." (PMID 27598148, 2016). "The healthy human lymph nodes contain mainly the CD56bright NK cell subset while in melanoma metastatic lymph nodes the CD56dimCD57+KIR+CCR7+ NK cell subpopulation prevails." (PMID 28082990, 2016). "Among them, C-C chemokine ligand 21/chemokine receptor 7 (CCL21/CCR7) pair promotes growth and metastasis of many tumor types including melanomas, breast, thyroid, colon, head, and neck cancers." (PMID 25744065, 2015). "In a screen of several melanoma cell lines it was detected that the expression of chemokine receptors CCR7, CCR10, CXCR1, CXCR2 and CXCR4 can dramatically increase the rate of metastases and define their preferential site." (PMID 26197340, 2015). "Pretreatment with an allogenic melanoma-derived cell lysate was capable of upregulating CCR7 expression on therapeutic human tumor presenting DCs and inducing migration to the lymph node." (PMID 25254213, 2014). "The correlation between CCR7 expression and lymph node metastasis was further verified by administration of neutralizing anti-CCL21 antibodies that markedly blocked lymph node metastasis of CCR7 expressing B16 melanoma cells." (PMID 23667660, 2013). "Following treatment with CCL19-myc and the 4A6 antibody, the melanoma cell line A375 that expresses endogenous CCR7 was specifically stained using a secondary peroxidase-conjugated antibody." (PMID 24068998, 2013). "Melanoma is a paramount example of a malignancy that acquires CCR7 expression in the metastatic state, as shown by the human A375 cell line variants: high expression of the chemokine receptor predicts the propensity for metastasis." (PMID 24068998, 2013). "Correlation between lymph node metastasis and CCR7 expression is observed in many cancers including esophageal squamous cell carcinoma, melanoma, non-small cell lung, head and neck, gastric, and colorectal." (PMID 24259307, 2013). "RT-PCR provided evidence for the presence of CCR7-mRNA in a human melanoma cell line, the A375 line." (PMID 24068998, 2013). "In fact, CCR7 is expressed in some malignant melanoma cell lines, and it has been shown in melanoma mouse model that lymphatics can attract cancer cells through secretion of endogenous chemokine." (PMID 22481918, 2012). "In vivo migration studies showed that CCR7 expression allows melanoma cells to migrate more efficiently toward depots of lymphatic endothelial cells." (PMID 24212647, 2011). "The theory of a CCR7-co-mediated mechanism of lymphatic dissemination was also supported by an animal study, revealing that the CCR7 expression of melanoma cells increases metastases formation in the regional lymph nodes of mice." (PMID 21548969, 2011). "The role of CCR7 as a mediator of LN homing capacity in melanoma as well as other cancers was highly suspected based on the known physiologic role of CCR7 in the homing of dendritic cells to lymphatic vessels and to secondary lymphoid organs." (PMID 24212647, 2011). "Novel engineered protein antagonists of CCR7 that bind CCL21 have been shown to block CCR7-mediated migration of melanoma cells in vitro and in vivo, raising the potential for therapeutically active CCR7 antagonists in patient care." (PMID 24212647, 2011). "Melanoma cells with relatively higher expression of CCR7 are more migratory in vitro when exposed to CCL21." (PMID 24212610, 2010). "Validation using three independent bulk RNA-seq datasets (cBioPortal: DFCI melanoma; ENA: PRJEB23709; GEO: GSE91061) suggested that CCR7 was associated with favorable ICI response and improved survival, whereas MTRNR2L2 showed a tendency toward enrichment in non-responders and poorer outcomes." (PMID 41758825, 2026).
melanoma (continued). "In addition, the level of CCR7 transcript in melanoma patients was related to the survival rate, indicating the potential role of cells expressing CCR7, including CD103+DCs, in anti‐tumor immunity." (PMID 36891351, 2023). "Wild-type C57BL/6J and Ccr7−/− mice were implanted with melanoma tumors and treated with ICT." (PMID 36867675, 2023). "CCL21 and CCR7 were both produced by melanoma tissue promoting an immunotolerant phenotype." (PMID 35203305, 2022). "Importantly, a recent study showed that the expression of CCR7 in human melanoma correlates with the levels of T-cell infiltration and patient survival." (PMID 36588582, 2022). "The current study investigated whether CCL21/CCR7 axis involves lymphatic metastasis of melanoma after chemotherapy." (PMID 35280672, 2022). "In vivo studies using B16 melanoma cells injected into nude mice showed that CCR7-expressing melanoma cells migrated more efficiently to lymphatic tissue in response to CCL21 that could be inhibited by a CCL21 neutralizing antibody." (PMID 35203305, 2022). "In summary, our data indicated that PTX treatment could increase lymphatic metastasis of B16F10 melanoma cells upon chemotherapy via the enhancement of the CCL21/CCR7 axis." (PMID 35280672, 2022). "A role for VEGF-C in inducing CCL21/CCR7-mediated lymphangiogenesis of melanoma cells was noted and a low percentage of melanoma cells expressed the immune checkpoint ligands, PD-L1 and galectin-9, resulting in cancer stem cell characteristics and increased metastasis." (PMID 35203305, 2022). "Nevertheless, the combination therapy targeting the CCL21/CCR7 axis and chemotherapy might provide a new direction for melanoma B16F10." (PMID 35280672, 2022). "In addition, increased VEGF-C and CCL21 staining was found in CCR7-expressing melanoma relative to control melanoma, further demonstrating a role for VEGF-C in lymphangiogenesis in mice." (PMID 35203305, 2022). "In a murine model of melanoma, when equal numbers of CCR7-overexpressing B16 mouse melanoma cells or control B16 cells were injected into footpads and tumor growth and protein expression were analyzed, tumor growth was not significantly different between CCR7+ melanoma and controls." (PMID 35203305, 2022). "Profiting from the amplified expression of CCR7, DCs pretreated with thyroid hormone triiodothyronine or allogeneic melanoma-derived cell lysate can move to dLNs and stimulate antigen-specific cytotoxic T-cell responses more effectively after being injected into melanoma animal models." (PMID 35281921, 2022). "Besides, CCR7 overexpressed and antigen modificatory DCs also show greater migratory ability to dLNs and more valid anti-tumor properties in melanoma and lung cancer." (PMID 35281921, 2022). "The blockade of CCL21/CCR7 axis may collectively serve as a strategy for lymphatic metastasis in some melanoma after chemotherapy." (PMID 35280672, 2022). "The CCL21/CCR7 signalling axis might be a superior target compared with other treatment strategies for treating patients with melanoma and lymph node metastasis." (PMID 35280672, 2022). "It is unclear whether CCL21/CCR7 signalling axis also plays a crucial role in promoting melanoma lymphatic metastasis after other chemotherapeutic drugs." (PMID 35280672, 2022). "This might indicate that CCR7 needs to be increased to a certain level to promote lymphatic metastasis of B16F10 melanoma after PTX treatment." (PMID 35280672, 2022). "Thus, inhibiting both the CCR7 and PD-L1 that are expressed on tumor cells can be considered a new approach to treating melanoma." (PMID 35768424, 2022). "The combined therapeutic effect of PTX and CCR7 mAb was tested in the B16F10 melanoma animal model." (PMID 35280672, 2022). "Furthermore, cancer-associated adipocytes led to the upregulation of chemokine ligands (CCLs)—CCL19 and CCL21—levels in the lymph nodes, as well as increased chemokine receptor 7 (CCR7) expression in melanoma cells." (PMID 33430277, 2021).